EIF4H (eukaryotic translation initiation factor 4H)
Diseases named in the same sentence as EIF4H in open-access papers:
EIF4H is named in the same sentence as 37 diseases in open-access papers, as found by Europe PMC text mining. Sharing a sentence is not in itself a finding about the gene and the disease. The quoted sentences say what the papers report.
glioma (5 papers, 2019 to 2023). A benign or malignant brain and spinal cord tumor that arises from glial cells (astrocytes, oligodendrocytes, ependymal cells). "In addition, TMZ significantly reduced the expression of 9 eIFs, including eIF3I and eIFH In a previous study, eIF3I and eIF4H were increased in gliomas and significantly associated with the overall survival of glioma patients." (PMID 37907716, 2023). "However, eIF3I and eIF4H were the only analyzed eIFs that were significantly associated with survival differences of glioma patients." (PMID 33807050, 2021). "In line with our previous study, we conclude that eIFs, especially eIF3I and eIF4H, are interesting candidates for future glioma therapy research." (PMID 37907716, 2023). "In conclusion, we identified eIF3I and eIF4H as the most promising targets for future therapy for glioma patients." (PMID 33807050, 2021). "This supports the hypothesis that eIF3I and eIF4H are of interest for future research on the improvement of glioma therapy." (PMID 37907716, 2023). "Reportedly, EIF4H is overexpressed in various cancers, such as colorectal cancer and glioma." (PMID 36101357, 2022). "As eIF4H and its interaction partner eIF4A1 seem to be relevant in gliomas, inhibiting the interaction between those two factors might be a novel approach in glioma therapy." (PMID 33807050, 2021). "Our work suggests eIF3I and eIF4H as potential targets for future glioma therapy." (PMID 33807050, 2021). "Therefore, targeting of eIF3I and eIF4H might represent a prospective approach towards improvement of glioma therapy." (PMID 33807050, 2021). "Protein and mRNA expressions of eIF3B, eIF3I, eIF4A1, eIF4H, eIF5 and eIF6 were significantly increased in high grade gliomas compared to CCBT and partially in low grade gliomas." (PMID 33807050, 2021). "However, the OS of glioma patients only correlated for eIF3I with LGG and for eIF4H with GBM." (PMID 33807050, 2021).
Williams syndrome (5 papers, 2015 to 2025). "This demonstrates that eIF4H depletion may contribute to certain deficiencies associated with Williams-Beuren Syndrome." (PMID 26498689, 2015). "The eIF4H gene is deleted in the Williams syndrome, a multisystem developmental disorder, and the specificity and level of depletion in therapeutic approaches is also likely to be critical." (PMID 35646086, 2022). "Recurrent breakage at this fragile site has been implicated in the Williams-Beuren syndrome and and this region contains the genes LIMK1, EIF4H(WBSCR1), AUTS2 as well as the tumor suppressor gene FZD9." (PMID 33444353, 2021). "Particularly, EIF4H is one of the genes deleted within 7q11.23 in patients with Williams Syndrome, which shares some phenotypic characteristics seen in ASD, while altered levels of APP and its metabolites have been identified in brain and plasma from autistic patients." (PMID 32060413, 2021). "The eIF4H gene is located within the Williams-Beuren Syndrome critical genomic region." (PMID 26498689, 2015). "eIF4H increases helicase activity of eIF4A. eIF4H gene is absent in a neurodevelopmental disorder called Williams syndrome." (PMID 40823305, 2025).
lung carcinoma (3 papers, 2015 to 2022). "Overexpression of EIF4H has been associated before with cell proliferation and increased chemoresistance in lung cancer." (PMID 36518527, 2022). "eIF4H is overexpressed in lung cancer cells and can be used to predict the response of chemotherapy." (PMID 35509884, 2022). "We evaluated the consequences of shRNA-mediated eIF4H depletion in A549 cells (lung carcinoma) and HeLa cells (cervical adenocarcinoma), by measuring drug-induced apoptosis, cell proliferation, migration and tumor growth." (PMID 26498689, 2015). "Given that eIF4H was highly expressed in lung carcinomas displaying resistance to chemotherapy, we first assessed the effect of eIF4H depletion on cisplatin or etoposide chemoresistance in vitro in A549 cells." (PMID 26498689, 2015). "Here we show that the two eIF4H isoforms are overexpressed in lung carcinomas and that the expression of this factor inversely correlates with the objective response to treatment." (PMID 26498689, 2015). "Here we show that eIF4H (eukaryotic translation initiation factor 4H), an activator of the RNA helicase eIF4A, is overexpressed in lung carcinomas and predictive of response to chemotherapy." (PMID 26498689, 2015). "We established that the expression levels of both eIF4H isoforms was significantly increased in lung carcinomas compared to corresponding healthy tissue." (PMID 26498689, 2015). "In lung cancer cells, depletion of eIF4H enhances sensitization to chemotherapy, decreases cell migration and inhibits tumor growth in vivo, in association with reduced translation of mRNA encoding cell-proliferation (c-Myc, cyclin D1) angiogenic (FGF-2) and anti-apoptotic factors (CIAP-1, BCL-xL)." (PMID 26498689, 2015). "Nevertheless, it is clear that eIF4H has differential effects on the synthesis of proteins involved in the resistance to chemotherapy and lung tumor progression, and that these effects could represent a novel approach to lung carcinoma intervention." (PMID 26498689, 2015). "eIF4H overexpression and its contribution to tumor growth are certainly not restricted to lung carcinoma." (PMID 26498689, 2015). "In this study, we have investigated the role of eIF4H in cellular transformation and its physiological role in mRNA translation both by overexpression of the two eIF4H isoforms in NIH3T3 cells and downregulation of the isoforms by RNA interference in lung cancer cells." (PMID 26498689, 2015).
viral infection (3 papers, 2020 to 2025). "As a translation initiation factor, Eif4h may play a role in this process by modulating the translation efficiency of mRNA in response to viral infection." (PMID 40547011, 2025). "Notably, the expression levels of the majority of these proteins increased following viral infection, with the exception of three proteins (Eif3h, Eif4h, and Csf1r), which exhibited downregulation." (PMID 40547011, 2025). "It is thought that constitutive expression of antiviral ISGs may protect from virus infection, but decreased protein translation (EIF4H) in PWH may minimize the contribution of antiviral ISGs that are constitutively expressed." (PMID 33064743, 2020).
Cognitive impairment (2 papers, 2017 to 2026). Abnormal cognition is characterized by deficits in thinking, reasoning, or remembering. "Transcripts predictive of cognitive performance under high stress included genes that are associated with a high occurrence of Alzheimer's and cognitive impairments (e.g., Ncl, Eno1, Scn9a, Slc19a3, Ncstn, Fos, Eif4h, Copa, etc.)." (PMID 28912681, 2017).
colon cancer (2 papers, 2015 to 2021). "Tumor type-specific eIF4H splicing variant expression was described previously for colon cancer cell lines." (PMID 33807050, 2021).
lung adenocarcinoma (2 papers, 2022). A carcinoma that arises from the lung and is characterized by the presence of malignant glandular epithelial cells. "In lung adenocarcinoma, eIF4H was the target of miRNA519d to inhibit cell proliferation and invasion." (PMID 35509884, 2022). "Based on the results of the present study, EIF4A1 interacting with EIF4H manipulates cell cycle regulation and immune microenvironment reprogramming in lung adenocarcinoma." (PMID 36101357, 2022).
amyotrophic lateral sclerosis (1 paper, 2022). Amyotrophic lateral sclerosis (ALS) is a neurodegenerative disease characterized by progressive muscular paralysis reflecting degeneration of motor neurons in the primary motor cortex, corticospinal tracts, brainstem and spinal cord. "In the post-mortem tissues of patients with amyotrophic lateral sclerosis and frontotemporal degeneration, eIF4H was downregulated in patients with G4C2 mutation compared to patients without the particular mutation and healthy controls, suggesting eIF4H as a disease modifier." (PMID 35509884, 2022).
astrocytomas (1 paper, 2021). "The product at 17 kDa might have been a degraded form of eIF4H or an astrocytoma-specific splicing variant." (PMID 33807050, 2021). "We showed that the expression of eIF3B, eIF3I, eIF4A1, eIF4H and eIF6 was significantly increased in astrocytomas, in particular in GBM, for protein and mRNA levels." (PMID 33807050, 2021). "Besides the already known eIFs, we demonstrated significantly elevated protein levels of eIF3D, eIF3H, eIF3I, eIF3M, p-eIF4G, eIF4H, eIF5 and eIF6 in astrocytoma tissue compared to CCBT." (PMID 33807050, 2021). "eIF4H-positive cells were only detected in astrocytoma samples and were almost absent in CCBT (I: p < 0.01, II: p < 0.001, III: p < 0.01, IV: p < 0.01)." (PMID 33807050, 2021).
coronary artery disease (1 paper, 2021). "Mutation of the human EIF4H gene is associated with coronary artery disease in humans." (PMID 34418970, 2021).
hepatocellular carcinoma (1 paper, 2023). A malignant tumor that arises from hepatocytes. "Next, we orthogonally validated the observed protective phenotypes of inactivated NFKBIA, EIF4E2, and EIF4H by generating knockout lines from Huh7.5.1 (hepatocellular carcinoma) cells ectopically expressing ACE2 and TMPRSS2." (PMID 37803001, 2023).
hypersomnia (1 paper, 2023). A sleep disorder characterized by excessive sleepiness. "Six (GPX4, PSMB5, PSMB6, PRDX5, ASNA1, EIF4H) out of seven hub genes were associated with the expression of insomnia/hypersomnia only in females, while UROD was the only hub gene common to both sexes." (PMID 37884562, 2023).
Intellectual disability (1 paper, 2024). "Furthermore, we identified one patient with a smaller 167.21-kb microdeletion within the WSCR, including EIF4H, LAT2, RFC2, and CLIP2, but not comprising the ELN gene and segregating in the family with non-syndromic intellectual disability." (PMID 39368701, 2024).
leukemia (1 paper, 2013). A malignant (clonal) hematologic disorder, involving hematopoietic stem cells and characterized by the presence of primitive or atypical myeloid or lymphoid cells in the bone marrow and the blood. "As expected, the RQ of EIF4H varied very little between leukemia samples when HNRNPL was used as the control gene (CV = 14%; MFC = 1.6)." (PMID 24069164, 2013). "These genes, including HNRNPL, EIF4H and PSMA1, were validated by qRT-PCR for use as control genes in leukemia." (PMID 24069164, 2013).
ZIKV infection (1 paper, 2019). "Moreover, other eukaryotic translation factors that were significantly up-regulated by ZIKV infection, although only ≈30%, include eIF4H and eIF5A-1." (PMID 30984137, 2019).
cancer (9 papers, 2011 to 2023). A tumor composed of atypical neoplastic, often pleomorphic cells that invade other tissues. "When RBM10 loss of function results in an increased exon 5 harboring EIF4H cancer-specific isoform, the alternatively spliced genes by EIF4H-L are considered as good putative targets." (PMID 34356101, 2021). "eIF4H, in contrast, had been associated with various diseases, most prominently cancer." (PMID 35509884, 2022). "EIF4H is a translation initiation regulator, and it is closely linked with cancer." (PMID 34356101, 2021). "The MDH2 and EIF4H genes show important roles in cancer growth and metastasis; thus, they are of clinical importance for cancer treatment." (PMID 36109686, 2023). "In a proteomic investigation of attached (surviving) and detached (dying) cancer cells, eIF4H was identified among six consistently differentially expressed proteins, and silencing it had an anti-proliferative effect." (PMID 35509884, 2022). "Despite extensive interest in the eIF4E, eIF4G and eIF4A components, few studies have addressed the function of eIF4A cofactors, namely eIF4H and eIF4B, in cancer progression." (PMID 26498689, 2015). "Interestingly, while KDM4A and PTK2 have apparently never been considered for gene expression normalization, the consistent expression of EIF4H has been demonstrated in human cancer cells, where it was proposed as a reliable control gene." (PMID 33183298, 2020). "Under these conditions, constitutively-active eIF4H could stimulate the translation of transcripts with complex 5′UTRs, conferring a relevant advantage to cancer cells for tumor growth, progression and resistance to chemotherapy." (PMID 26498689, 2015). "eIF4H, PABP) would yield a similar or even greater therapeutic potential in the treatment of cancer." (PMID 21378410, 2011).
tumor (9 papers, 2013 to 2023). "In this regard, the expression of a spliced isoform of eIF4H was shown to be strictly associated with the tumour behaviour and increased translation rate of peculiarly structured 5′cap mRNAs, including those of proliferative functions, such as cyclin D1." (PMID 23776612, 2013). "The encoded translation initiation factors of EIF4H can be used to stimulate the initiation of protein synthesis at the level of mRNA utilization, controlling this gene translational may make key contribution translational control in tumor promotion." (PMID 29026100, 2017). "In our study, the expression of EIF4H was upregulated in the tumor tissues of LUAD patients who had poor clinical outcomes." (PMID 36101357, 2022). "EIF4H knockdown significantly inhibited A549 cell tumor growth compared with control groups (P < 0.001 at day 35)." (PMID 26498689, 2015). "BCAT1 suppression in SKOV3 cells led to the induction of several gene nodes (EIF5A2, EIF5 and EIF4H), as part of the eukaryotic initiation factors (eIFs) network, shown to display all elements of a complete oncogenic, as well as tumor suppressive cascade." (PMID 26372729, 2015). "We first investigated eIF4H expression in various tumor types using a high-density multiple organ tumor and normal tissue array, which contains 18 types of tumor alongside normal controls (MC5003, Biomax, US)." (PMID 26498689, 2015). "eIF4H total protein expression in these tumors was confirmed by immunohistochemistry using histological sections of tumor (T) and adjacent normal tissue (N)." (PMID 26498689, 2015). "Taken together, these data indicate that eIF4H expression not only enhances the resistance of tumoral cells to chemotherapeutic drugs but also promotes tumor growth and angiogenesis in nude mice." (PMID 26498689, 2015). "Taken together, these data demonstrate that eIF4H overexpression protects against drug-induced apoptosis in vitro, but also promotes cell proliferation, migration, invasion, and tumor growth." (PMID 26498689, 2015). "A similar evidence was reported for eIF4B, the human paralogue of eIF4H, which promoted the tumour growth and increased the translation of mRNAs harbouring 5′UTR secondary structures, including oncogenes." (PMID 23776612, 2013). "Taken together, these results suggest that eIF4H may contribute to tumor progression by promoting the expression of potent growth and survival factors." (PMID 26498689, 2015). "Conversely, each isoform of eIF4H acts as an oncogene in NIH3T3 cells by stimulating transformation, invasion, tumor growth and resistance to drug-induced apoptosis together with increased translation of IRES-containing or structured 5′UTR mRNAs." (PMID 26498689, 2015). "The IDH1 (R132H) mutation had no significant impact on expression status of eIF3I or eIF4H positive tumor cells.Error bars are partly missing because of the low number of samples or similar tissue intensity scores in the immunohistochemical evaluation." (PMID 33807050, 2021). "Notably, eIF3I but not eIF4H significantly correlated with tumor size reduction after TMZ treatment." (PMID 37907716, 2023). "The expression of EIF4H at mRNA levels, but not EIF4B, was enhanced in the tumor tissue of patients with LUAD." (PMID 36101357, 2022).
infection (5 papers, 2015 to 2024). The state of being infected such as from the introduction of a foreign agent such as serum, vaccine, antigenic substance or organism. "We further identified the NF-κB inhibitor IκBα (NFKBIA), as well as the translation factors EIF4E2 and EIF4H as strong host dependency factors acting early in infection." (PMID 37803001, 2023). "The second translation factor that conferred protection from infection upon knockdown, EIF4H, binds to and stimulates RNA helicase activity of EIF4A48,49." (PMID 37803001, 2023). "Moreover, siRNA mediated knockdown of eIF4H result in a decline in the activity of vhs in degrading host mRNA early after infection, independent evidence that eIF4H is specifically involved in vhs mRNA degradation and thus translational suppression." (PMID 30028874, 2018). "The fact that the NCL-eIF4H interaction selectively occurs during lytic but not latent KSHV infection suggests that this interaction is facilitated by NCL relocalization to the cytoplasm, although infection could also alter the translational requirements for eIF4H." (PMID 25965334, 2015). "More specifically, levels of eIF5A, eIF5B, eIF1A, eIF4H proteins, and ribosomal proteins 40S and 60S were significantly decreased in PAMs after HP-PRRSV HN07-1-infection." (PMID 35498732, 2022). "Compared to non-targeting controls, ACE2, NFKBIA, EIF4E2, and EIF4H knockout cell lines showed a substantial decrease in infection." (PMID 37803001, 2023). "We first considered that eIF4H relocation could be a general effect of infection, independent of vhs activity." (PMID 30028874, 2018). "NFKBIA knockout cells displayed a 31.8% decrease in infection, 85.5% in EIF4E2 KO, and 33.2% in EIF4H KO cells compared to non-targeting control cells." (PMID 37803001, 2023). "Notably, the protective phenotypes when targeting EIF4E2 and EIF4H do not appear to reflect a general effect of perturbing translation factors, as EIF4B did not significantly alter infection dynamics." (PMID 37803001, 2023).
neurodegenerative disease (1 paper, 2022). A disorder of the central nervous system characterized by gradual and progressive loss of neural tissue and neurologic function. "eIF4h has been found to be associated with neurodegenerative diseases as well." (PMID 35509884, 2022).
psychiatric disorder (1 paper, 2022). A disorder characterized by behavioral and/or psychological abnormalities, often accompanied by physical symptoms. "It is the first time HYI and eIF4H were found to associate with psychiatric disorders." (PMID 35509884, 2022).
EIF4H also shares sentences with these, for which no sentence is quoted: breast carcinoma (3 papers); B-cell lymphoma (1); bladder cancer (1); cervical adenocarcinoma (1); colorectal cancer (1); coronary atherosclerosis (1); COVID-19 (1); emphysema (1); esophagus cancer (1); glioblastoma (1); heart disease (1); insomnia (1); neuroblastoma (1); neurodevelopmental disorder (1); preeclampsia (1); Sepsis (1); small cell lung carcinoma (1).